DCAF8L2 (DDB1 and CUL4 associated factor 8 like 2)
Synonyms: WDR42C
Tractability: No criterion of Open Targets' tractability assessment is met for any kind of drug.
Gene: Protein-coding gene on chromosome X (27,590,281 to 27,749,942, forward strand). Ensembl gene ENSG00000189186.
Gene Ontology:
Cellular component: Cul4-RING E3 ubiquitin ligase complex
Homologues: Orthologues: chimpanzee DCAF8L2 (98% identical), macaque DCAF8L1 (93% identical), tropical clawed frog dcaf8 (61% identical), rat AABR07038690.1 (56% identical), mouse Dcaf8l (55% identical), zebrafish dcaf8 (51% identical), Drosophila melanogaster CG8001 (31% identical). Paralogues in human: DCAF8L1 (76% identical), DCAF8 (67% identical), DCAF6 (24% identical), WDTC1 (21% identical), DCAF5 (16% identical).
Diseases named in the same sentence as DCAF8L2 in open-access papers:
DCAF8L2 is named in the same sentence as 2 diseases in open-access papers, as found by Europe PMC text mining. Sharing a sentence is not in itself a finding about the gene and the disease.
DCAF8L2 shares sentences with these, for which no sentence is quoted: neuropathy (1 paper); tumor (1).